IGFBP3 (insulin like growth factor binding protein 3)
Diseases named in the same sentence as IGFBP3 in open-access papers (continued):
Sharing a sentence is not in itself a finding about the gene and the disease.
tumor (continued). "Therefore, on the basis of tumor expression rate, IGFBP-3 holds some promise as vaccine target because it suggests that around 43% of CRC patients could benefit from an IBF2BP3-based vaccine." (PMID 26244168, 2015). "Whether tumor stage may also influence IGFBP3 action is poorly understood." (PMID 25374561, 2014). "Furthermore, overexpression of COX-2 by tumor cells downregulates IGFBP-3 mRNA expression." (PMID 23833672, 2013). "Thus, it might be expected that both promoter methylation and histone-deacetylation may play important roles in the control of the IGFBP3 tumor suppressor in the liver." (PMID 22401581, 2012). "In addition to its direct effects on cancer cells, IGFBP3, as a secreted protein, may also have paracrine effects on the tumor environment." (PMID 19903356, 2009). "Osteopontin (OPN) and insulin-like growth factor binding protein 3 (IGFBP3) are multifunctional proteins involved in regulating cell proliferation and tumor progression, with potential roles for early cancer detection." (PMID 41564382, 2026). "Our results demonstrate that m6A sites in the 3′UTR of IGFBP3 play a key role in recruiting and binding IMP3, which is involved in gene regulation and modulation of tumour cell proliferation." (PMID 40621649, 2025). "Curiously, IGFBP-3 and IGFBP-7 have been found to be induced by TGF-β1 expression and activate TGF-β receptors in a tumor context." (PMID 41226289, 2025). "Tumor tissues exhibited substantial upregulation of TFF1, UBE2C, ITPKA, and IGFBP3, alongside concurrent downregulation of SELENBP1 and SLC34A2, relative to matched normal samples." (PMID 40787454, 2025). "In brief, IGFBP-1, IGFBP-2, IGFBP-3, and IGFBP-5 have been shown to elevate PD-L1 expression on macrophages and tumor cells, leading to reduced immune response in gliomas, esophageal, and colorectal cancers." (PMID 41226289, 2025). "TCGA analysis demonstrated that IGFBP3 upregulation dramatically impacted HCC patient survival outcomes including the overall survival (OS) rate and tumor‐free survival rate (DFS)." (PMID 38463397, 2024). "Our findings unveiled a significant upregulation in a variety of cytokines in UPP1-overexpressing tumor cells, including TGF-β1, GM-CSF, IL-1β, IL-6, IGFBP-3, CXCL5, CCL20, and VEGF, with TGF-β1 being the most prominently elevated." (PMID 38331898, 2024). "Together, IGFBP-2 and IGFBP-3 exemplify the complexity of IGF regulation in cancer biology, with their distinct roles contributing to the multifaceted nature of tumor development." (PMID 39585162, 2024). "Upon analyzing the expression of 11 model genes in prostate PRAD, we observed significant differential expression of eight genes (MYADM, MPDZ, LTBP2, DENND4C, PROK1, DDIT4, IGFBP3, and CFD) between normal and tumor tissues." (PMID 38898043, 2024). "For example, GPX3, VIM, and IGFBP3 are known to be important markers in clear cell RCC,31,32,33 but much less is known about their patterns of spatial expression within the tumor." (PMID 37426750, 2023). "Inter-tumor Core and Rim regions showed significantly higher relative expression of hypoxia response genes, including LDHA, VEGFA, LOX, PLAUR, SERPINE1, and IGFBP3." (PMID 37434262, 2023). "The Chi-square analysis exhibited that high IGFBP3 was negatively correlated with tumor stage, extranodal infiltration, LDH levels, and IPI score, which demonstrated IGFBP3 involved in repressing ABC-DLBCL clinicopathological progression." (PMID 36660244, 2023). "On the other hand, IGFBP-3, the most abundant IGFBP in circulation, is involved in anti-tumor functions such as inhibition of cell proliferation and induction of apoptosis and cell cycle arrest." (PMID 38137390, 2023).
tumor (continued). "Insulin-like growth factor binding protein-3 (IGFBP-3) is a member of the IGFBP family that has high affinity for IGFs and functions as either an oncogene or tumor suppressor in various types of cancer." (PMID 35798794, 2022). "The inhibition of xenograft GBM tumor growth by miR-21 silencing was reversed by IGFBP-3 knockdown, suggesting that miR-21 oncogenesis is mediated by IGFBP-3 suppression." (PMID 35597813, 2022). "Studies have shown that the affinity of Igfbp3 for IGF-I/II was lost when its residues I56, L80, and L81 were substituted by glycine (G), which prevented apoptosis and also promoted the tumor growth in vivo and in vitro." (PMID 35754836, 2022). "At the end of therapy for the hCG-secreting tumor, two patients with pineal lesions had an IGF-1 level higher than 2 SD, and meanwhile only one patient with pineal involvement had an IGFBP-3 level higher than 2 SD." (PMID 36425849, 2022). "Taken together, these data uncover a regulatory mechanism by which AR deletion induces IGFBP3 expression in Gli1-lineage FB to block IGF1-signaling activation, further hindering prostatic basal epithelial cell-mediated oncogenesis and tumor development." (PMID 36323713, 2022). "Aberrantly increased IGFBP3 impairs IGF1-induced Wnt signaling activation in subsets of basal epithelial cells, directly inhibiting prostatic epithelial oncogenic growth and tumor development." (PMID 36323713, 2022). "Animal experiments have shown that tumor-derived factors such as IL-6, CXCL16, IFNγ, TNFα, and IGFBP-3 positively regulate the expression of CD38, and high expression of CD38 can enhance the immunosuppressive and tumor-promoting capacity of MDSCs." (PMID 36119033, 2022). "This complex reduces a collection of genes, including insulin-like growth factor-binding protein 3 (IGFBP3), a tumor suppressor, by regulating gene transcription." (PMID 35159030, 2022). "Specifically, IGFBP3 was reported to inhibit tumorigenesis and cell growth, and IGFBP5 was suggested to function as a tumor suppressor." (PMID 35688943, 2022). "The tumor-suppressive role of miR-196b is supported by the findings that it regulates MYC and ERG and that it binds the 3′-UTR region of IGFBP3 mRNA (reversible by resveratrol in vitro)." (PMID 36010971, 2022). "IGFBP3, a member of IGFBP family, had been reported that it can halt cell proliferation, promote cell apoptosis and reduce tumor growth." (PMID 36409444, 2022). "The results indicated that the expression of tumor cell-derived VEGFA, IGFBP3, EFNA1, EFNB1, IGF2, PDGFA and stroma-derived Angpt2, Cdh5, Esam, Esm1, Icam2, and Tie1 was statistically correlated with that of Pecam1 and elevated in p-EMT TW2.6 tumors." (PMID 34869001, 2021). "Another study examined tumor tissues and adjacent tumor-free tissues from 86 STAD patients; the results showed that IGFBP3 expression was higher in the tumor-free tissues, and high IGFBP3 expression predicted better prognosis." (PMID 34745945, 2021). "Thus, IGFBP3 may have context-dependent tumor-promoting or -suppressing activities." (PMID 33712045, 2021). "The first group included CA9, NDUFA4L2, EGLN3, BHLHE41, VWF, IGFBP3, and ANGPTL4, whose expression levels were coordinately decreased during tumor progression." (PMID 34046336, 2021). "Therefore, we could clarify the clinical roles of IGFBP3, HIF-1α and HIF-2α in EOC progression: HIF-1α being important in early hypoxia response and HIF-2α playing in prolonged hypoxia that could be associated with the overcome of tumor growth restriction." (PMID 34824343, 2021). "Insulin increases the breakdown of IGFBP-3, thus increasing the levels of free IGF-1, promoting tumor formation." (PMID 34359595, 2021).
tumor (continued). "Given the reported biological significance of interactions between IGF-I, IGFBP-7, and IGF-IR, correlations between preoperative circulating IGF-I, IGFBP-3, and IGFBP-7 levels, and tumor IGF-IR membrane (IGF-IRm) expression were assessed." (PMID 33767994, 2021). "Age-adjusted geometric means with 95% Wald confidence intervals (CIs) of IGF-I, IGFBP-3, IGFBP-7, and IGF-I/IGBP-3 molar ratios in relation to patient and tumor characteristics." (PMID 33767994, 2021). "Meanwhile, IGFBP3 downregulation also led to the suppression of the EMT, indicating its tumour-promoting effect." (PMID 34512163, 2021). "The expression of the IGFBP3 gene is coordinated with BHLHE41 as well as with other HIF-1α-activated genes, decreasing in expression as the tumor grows." (PMID 34046336, 2021). "Tumor growth is promoted by activating proliferation (BHLHE41, VWF, ANGPTL4, and possibly IGFBP3), and preventing the apoptosis of cancer cells (ANGPTL4)." (PMID 34046336, 2021). "Tumor expression of TGFBI, IGFBP3, and CHI3L1 were positively correlated with PDGFD and PDGFRB expression in TCGA LGG dataset, respectively." (PMID 34539622, 2021). "At the initial stage of tumor development, BHLHE41 expression correlated with that of VWF and IGFBP3 expression." (PMID 34046336, 2021). "We demonstrated a novel mechanism of tumor invasion and metastasis in NSCLC that involves the activation of the XBP1/IGFBP3/MMP-9 pathway." (PMID 34094948, 2021). "IGFBP-3 is a critical regulatory molecule in the IGF system and can function in a tissue-specific manner as either a tumor suppressor or tumor promoter." (PMID 32742448, 2020). "In this study a homogeneous tumor group has been detected, which is characterized by FTV, increased VD, and upregulation of VEGF, PlGF, and IGFBP-3 expression." (PMID 33096816, 2020). "Immunohistochemical analyses confirmed strong correlations between tumor vessel fibrosis and expression of VEGF, PlGF, and IGFBP-3." (PMID 33096816, 2020). "However, the clinical importance of tissue IGFBP-3 levels may differ among different tumour types." (PMID 32093285, 2020). "TPX2 siRNA upregulated the expression of IGFBP-3, resulting in significantly reduced CD34-positive micro vessels in the tumor." (PMID 33033514, 2020). "In summary, we show that Galectin-3 modulated angiogenesis- and EMT-driven metastasis via activation of the β-catenin signalling cascade by targeting IGFBP3 and vimentin in the HCC tumour microenvironment." (PMID 32801345, 2020). "IGFBP2 is the second most abundant IGF-binding protein (after IGFBP3), functions as a carrier for IGF-1 and likely promotes tumor progression through IGF-1R pathway." (PMID 31399589, 2019). "Thus tissue effects of IGFBP-3 may largely be attributable to local (tissue and tumor) production." (PMID 28778177, 2017). "On the other hand, the IGFBP3 is known to bind IGF1 as well as IGF2 and have an anti-tumor effect in several types of cancers and its concentration decreases markedly in circulation of cancer patients." (PMID 28223541, 2017). "In vitro studies suggest that IGFBP-3, which potentiates EGFR signaling via activation of SphK1, is a driver of proliferation in these tumors and its measurement in tumor tissue should be evaluated as a potential biomarker of drug combination efficacy." (PMID 28778177, 2017). "With different from IGF-1, insulin-like growth factor binding protein 3 can limit the bioactivity of IGF-1, and exerts its action of inhibiting tumor cell growth." (PMID 27835910, 2016). "Mammalian and zebrafish IGFBP-3/Igfbp-3 has a functional NLS and can be found in the nucleus of cultured tumor cells." (PMID 28149290, 2016).
tumor (continued). "In this study, the value of the serum tumor markers CA19.9, CEA, CRP, albumin, IGF-1 and IGFBP3 alone or in combination, in the differential diagnosis of PDAC and CP was assessed." (PMID 26808421, 2016). "Furthermore, significant association was observed between the low IGFBP-3 level and clinical pathological characteristics including the tumor category and survival status rather than the age, gender, tumor location, and tumor size of patients in current meta-analysis." (PMID 27978831, 2016). "Insulin-like growth factor binding protein-3 (IGFBP-3) is a key regulatory molecule of the IGF axis and can function in a tissue-specific way as both a tumor suppressor and promoter." (PMID 26221601, 2015). "The average tumor area of lymph nodes was 0.153 ± 0.054, 0.087 ± 0.054 and 0.033 ± 0.016 mm2 in mice with control cells, LN1–1 IGFBP3 sh4 and sh5 cells, respectively." (PMID 26540630, 2015). "For IGFBP-3 immunohistochemical staining in ESCC tissues, immunoreactivity was observed as areas of yellowish-brown color primarily in the cytoplasm within tumor cells." (PMID 26370590, 2015). "To address the clinical significance of up-regulated IGFBP3 mRNA in OSCC, we observed insignificant correlations with clinicopathological parameters, including pathological stage, and tumor status." (PMID 26540630, 2015). "We also found five TSG-type genes that were thought to act as tumor suppressor genes because they exhibited DNA methylation features similar to those observed in the BMP4 and IGFBP3 genes." (PMID 26421064, 2015). "Thus, IGFBP3 may have context-dependent tumor-promoting activities." (PMID 26540630, 2015). "So far, only one study reported the positive correlations between the IGFBP3 protein-positive grade in OSCC tissue and the tumor size as well as lymph node metastasis." (PMID 26540630, 2015). "Three days after tumor injection, mice received intraperitoneal (i.p.)injections of saline, or 0.37 mg/Kg or 1.87 mg/kg IGFBP-3 three times a week (TTW) for three weeks and tumor growth was estimated during the follow-up." (PMID 24905466, 2014). "IGFBP3 and IGFBP6 are IGF-binding proteins that inhibit IGFs, therefore functioning as tumor suppressors." (PMID 24920244, 2014). "The importance of IGFBP-3 in the regulation of NSCLC cell proliferation, clonogenicity, and tumour growth was shown in an in vitro study by the same group." (PMID 24339922, 2013). "Nevertheless, technical restrictions, such as heterogeneity of tumor samples, which comprise the stromal components and the adjacent normal liver tissue in low proportions, might have contributed to an underestimation of HB cases with a methylated IGFBP3 promoter in our study." (PMID 22401581, 2012). "IGFBP-3 can therefore reduce IGF-1 bioavailability and inhibit IGF-1 interaction with the IGF-1 receptor, thereby functioning as a tumor suppressor." (PMID 22879989, 2012). "Combined IGFBP3 and trastuzumab treatment resulted in a statistically significant reduction in MCF7/HER2 xenograft tumor volume." (PMID 22830017, 2012). "The tumor endometrium expressed significantly lower levels of IGF-1, IGF-1R, and IGF-2, and significantly higher levels of IGF-2R and IGFBP-3, compared with tumor-adjacent endometrium (p < 0.05)." (PMID 22720981, 2012). "CFD/Adipsin median levels were found to be lower in tumours compared to the levels in PN and AN (p = 0.0324), while CXCL5/ENA78, CCL20/MIP-3α, IGFBP3, SPP1/OPN and TIMP1 were increased in PN and tumours relative to AN, with higher levels seen in tumours." (PMID 21092330, 2010). "Here, we present evidence that IGFBP3 has dual, opposing effects on GIST cell viability and that IGFBP3 partially mediates the anti-tumor effects of imatinib mesylate in some GISTs in vitro." (PMID 19903356, 2009).
tumor (continued). "Previously, we found up-regulation of insulin-like growth factor binding protein-3 (IGFBP3) expression in imatinib-responsive GIST cells and tumor samples." (PMID 19903356, 2009). "We also found in the study that TGF-β1 levels in tumour tissues were positively correlated with the concentrations of IGF-I, IGF-II, and IGFBP-3." (PMID 18827819, 2008). "In all 49 tumours and 6/7 HGPIN that showed IGFBP3 methylation, methylation of GSTP1 was also detected." (PMID 17453001, 2007). "Elevated IGFBP3 activated AKT signalling and promoted tumour progression." (PMID 40621649, 2025). "The qRT-PCR results revealed pronounced upregulation of TFF1, ITPKA, UBE2C, and IGFBP3, along with marked downregulation of SLC34A2 and SELENBP1 in tumor samples relative to adjacent normal tissues, which was in strong agreement with the transcriptomic profiling outcomes." (PMID 40787454, 2025). "Here, the expression of COL5A3, FN1, and NOTCH3 was more specific to α-SMA-positive stromal cells rather than tumor cells, while IGFBP3 was overexpressed in both tumor and stroma in comparison to adjacent non-tumor tissues." (PMID 40522948, 2025). "While IGFBP3 was clearly expressed in TECs, we found that ACKR1 was instead expressed in a transitional subpopulation of ECs derived mainly from normal kidney tissue with a smaller contribution of ECs isolated from the tumor." (PMID 39516665, 2024). "Correlating with the scRNA-seq data, RNA-ISH for IGFBP3 showed weak expression in rare peritubular capillaries and some tubules, whereas it showed strong expression in the RCC vasculature and patchy expression in the tumor cells themselves." (PMID 39516665, 2024). "After that, we re-subtypeed tumor cells, and annotated them according to each cell marker gene, and identified six tumor cell subtypes: C0 XIST+ tumor cells, C1 SCGB2A1+ tumor cells, C2 IGF2+ tumor cells, C3 UBE2C+ tumor cells, C4 TFF3+ tumor cells and C5 IGFBP3+ tumor cells." (PMID 39896800, 2024). "Versus mice fed an isocaloric Western diet (44% kcal of carbohydrates), mice fed a no-carbohydrate diet had prolonged survival, smaller tumors, reduced insulin, and increased insulin-like growth factor-binding protein 3 (IGFBP3), which has tumor suppressing activity." (PMID 38082056, 2024). "Interestingly, based on previous studies, IGFBP3 targets the regulation of classical signaling pathways and key molecules such as MAPK, EGFR, AKT, and EMT to regulate tumor proliferation and metastasis." (PMID 38463397, 2024). "On the other hand, other players in the system, such as IGF binding protein 3 (IGFBP3), the GH-IGF system, and IGF-II receptors, prevent the induction of apoptosis, promote mitogenesis, and control IGF-I activities, which operate as tumor growth inhibitors." (PMID 36675591, 2023). "Additionally, TIMP3, SPARC, IGFBP3, and IGFBP7 were highly expressed in the Mac_5 cluster, and these genes were involved in immunosuppression, tumor cell proliferation, and angiogenesis." (PMID 37533434, 2023). "Again, this is consistent with previous reports of an IGFBP-2 correlation with an increased malignant status of the tumor but not IGFBP-3." (PMID 38137390, 2023). "Comparison of normal and tumor tissue at long-term culture showed increased expression of IGF1R (5-fold, p < 0.0001) and IGFBP6 (3.5-fold, p < 0.01), whereas IGFBP1 (4-fold, p < 0.05), IGFBP3 (2.5-fold, p < 0.01) and IGFBP4 (4-fold, p < 0.01) were downregulated in tumor slices." (PMID 35884847, 2022). "For example, a patient, regardless of age or sex, with TNM I stage, Tumor size > 5 cm, and serum IGFBP3 ≤ 1000 ng/ml had a total of 168 points indicating an estimated 1-, 3-, and 5-y OS of 73%, 30%, and 22%, respectively." (PMID 36409444, 2022). "Tumor miR-125a was inversely associated with IGFBP-3 mRNA and, although no survival data were presented for IGFBP-3, its low tumor expression was correlated with increased tissue Akt activation." (PMID 35597813, 2022).